GDF15 (growth differentiation factor 15)
Diseases named in the same sentence as GDF15 in open-access papers (continued):
Sharing a sentence is not in itself a finding about the gene and the disease.
Stroke (continued). "Additionally, a 3-fold increase in GDF15 gene expression was noted in the contralateral cortex, reaching statistical significance only in the right stroke group." (PMID 39008451, 2024). "In a sub-analysis from the ARISTOTLE trial, including more than 18,000 patients with atrial fibrillation randomized to either apixaban or warfarin, GDF-15 predicted major bleeding events, stroke or systemic embolism and mortality, independently of NT-proBNP or hs-cTnI." (PMID 39200768, 2024). "The impact of increased GDF15 in the heart following a stroke remains to be established." (PMID 39008451, 2024). "Circulating GDF-15 was associated with subclinical brain injury and cognitive impairment in patients, but not with the appearance of stroke." (PMID 38398274, 2024). "The mentioned study had a limited scope as it solely encompassed a single sampling time prior to the occurrence of stroke, without investigating the association between GDF-15 levels and the subsequent outcome." (PMID 37446186, 2023). "After adjusting for clinical factors, GDF-15 was independently associated with CV mortality, non-CV mortality, and stroke, but not MI." (PMID 36676179, 2023). "In these seminal trials, when multivariable analyses including other biomarkers were performed, GDF-15 was no longer independently associated with stroke/systemic embolism." (PMID 31280356, 2020). "However, the cardioprotective potential of GDF15 may find application in other situations, such as conditions involving the stroke-heart syndrome." (PMID 38839839, 2024). "Therefore, the observed elevation of GDF15 in these brain regions might be attributable to small embolic strokes occurring in this area." (PMID 39008451, 2024). "Therefore, we can hypothesize that the increased GDF-15 concentration in stroke patients may originate both from the pre-ischemic context of high risk factors in an elderly population and from the acute ischemic inflammatory event." (PMID 31258506, 2019). "Similar to CHD and HF, higher concentrations of GDF15 and IL6, along with TNFR1, Eotaxin, MMP1, and MMP2, conferred the highest HRs for incident stroke." (PMID 39695064, 2025). "Of note, the AUCs for GDF-15, D-dimer, ADAMTS13, CCL2/MCP-1, IL-4, CC4b, IL-7, ferritin, SAA, CCL1/I-309 and IL-10 were ≥0.75 in indicating stroke amongst children with TBM." (PMID 33930055, 2021). "The effects of apixaban in reducing stroke, mortality, and bleeding were consistent irrespective of GDF-15 levels, but no data is shown if apixaban had any influence on the levels of GDF-15 to mitigate inflammation." (PMID 39201414, 2024). "In this study, there was a linear relationship between increasing GDF-15 levels and the primary endpoint defined as a composite of CV death, nonfatal MI, or nonfatal stroke." (PMID 36676179, 2023). "Our findings for MI and stroke are consistent with those from previous studies and published meta-analyses, with very similar effect sizes for CRP, NT-proBNP, and GDF-15." (PMID 34935094, 2022). "GDF-15 was elevated to an immeasurably high level on day 0, especially between 8 and 20 hours after the onset of the stroke-like episode (data not shown)." (PMID 31630688, 2019). "It was not possible to clearly establish whether GDF-15 levels increase with stroke volume since no systematic MRI assessment was done." (PMID 31258506, 2019). "In the total population as well as in the non-CVD population an increasing GDF-15 level was significantly and log-linearly related to total and CVD mortality as well as to CHD and stroke morbidity and mortality and to cancer mortality." (PMID 24312445, 2013). "However, GDF-15 was proven not predictive of combined ischemic endpoints of (non-fatal MI, UA, unplanned revascularization, ST, TIA and stroke)." (PMID 27056183, 2016).
colon carcinoma (59 papers, 2008 to 2025). "Esophageal, breast, and colon cancer models show that GDF-15 correlates with the loss of E-cadherin and that the inhibition of GDF-15 expression decreases cell migration and invasion ability." (PMID 39000420, 2024). "Our results show that the low expression of GDF15 contributes to 5-FU resistance in human colon cancer by regulating EMT and apoptosis via a Smad-associated signaling pathway." (PMID 33062674, 2020). "GDF15 also associated with senescence to promote colon cancer formation, and human airway epithelial senescence." (PMID 32857481, 2020). "Overall, our findings suggest that 5-FU resistance in colon cancer cells is associated with the repression of GDF15 and the subsequent enhancement of the EMT and antiapoptotic ability of cancer cells." (PMID 33062674, 2020). "Previous studies have confirmed that GDF15 is closely associated with tumor stem cells and can be used as a marker to reflect the prognosis of colon cancer." (PMID 33062674, 2020). "In our study, we found that 5-FU resistance was caused due to the inhibition of GDF15 and the downstream Smad signaling pathway in colon cancer." (PMID 33062674, 2020). "Although the upregulation of the SASP component GDF15 has been associated with many types of cancers, including colon cancer, its pro-tumorigenic role remains unclear and context-dependent." (PMID 36059680, 2022). "In addition, capsaicin-induced GDF-15 causes apoptosis in colon cancer cell lines such as HCT116 cells." (PMID 36008442, 2022). "Consistent with previous studies, the present findings demonstrate that 5-FU resistance in colon cancer cells is mechanistically associated with their enhanced migration and antiapoptotic ability by inhibiting the expression of GDF15 and related signaling pathways." (PMID 33062674, 2020). "For example, human cohort studies have reported GDF15 as a biomarker of cardiovascular disease, cardiovascular and cancer mortality and morbidity, renal disease, and all-cause mortality independent of cardiovascular mortality, as well as a driver of senescence-associated colon cancer metastasis." (PMID 31945054, 2020). "The proposed mechanism was increased phosphorylation of c-Fos via Erk1/2 activation by GDF-15, which induced the expression of epithelial–mesenchymal transition in colon cancer cells." (PMID 39000420, 2024). "These and previous corroborating findings from colon cancer, glioma and benign atrophic lesions of the human prostate can be explained by the newly discovered GDF-15-dependent inhibition of LFA-1 on immune effector cells." (PMID 37474523, 2023). "GDF15 promotes cell proliferation, migration, and invasion in colon cancer via the MAPK and PI3K signaling pathways." (PMID 36532065, 2022). "In vitro, senescent fibroblasts promoted the proliferation of both adenoma and colon cancer cells via the secretion of the SASP component growth differentiation factor 15 (GDF15)." (PMID 36059680, 2022). "Our findings will provide new insights into the potential of GDF15 as a novel anti-angiogenic target for colon cancer therapy." (PMID 33193874, 2020). "Quantitative reverse transcription-PCR and western blotting revealed that 5-FU-resistant colon cancer cells expressed lower levels of growth differentiation factor 15 (GDF15) than did 5-FU-sensitive colon cancer cells." (PMID 33062674, 2020). "Previous research has shown that GDF15 was involved in the migration of colon cancer and lung adenocarcinoma by regulating the TGF‐β/Smads signaling pathway." (PMID 33098235, 2020). "Our results also supported the potential of the GDF15-POSTN axis as a novel target for the development of new anti-angiogenic therapies in colon cancer." (PMID 33193874, 2020). "We identified GDF15 as a major SASP factor in the colon of people with concurrent advanced colon neoplasms and showed it is secreted by senescent colon fibroblasts." (PMID 31389184, 2019).
colon carcinoma (continued). "In cancer, GDF-15 overexpression has been reported in malignant melanomas, prostate-, pancreatic- and colonic cancers." (PMID 30645608, 2019). "While we principally demonstrate the feasibility of our protocol for the analysis of biomarkers in human serum, future analysis will be needed to evaluate the prognostic value of DcR3 and GDF15 for colon cancer patients using large patient cohorts." (PMID 25823874, 2015). "Our proof-of-principle studies in patient sera encourage the future analysis of the prognostic value of DcR3 and GDF15 for colon cancer patients in larger patient cohorts." (PMID 25823874, 2015). "HIF-induced JMJD1A expression at 0.5% oxygen caused increased histone demethylation leading to the induction of the adrenomedullin (ADM) and growth and differentiation factor 15 (GDF15) genes, which promote tumor growth in renal and colon cancer cell lines." (PMID 26426056, 2015). "For example, enforced MIC-1/GDF15 overexpression in HCT-116 colon cancer cells or in the DU145 PCa cell line, xenografted into immunodeficient mice, reduced tumor size." (PMID 25695521, 2015). "Patients with colon cancer who have elevated serum MIC-1/GDF15 levels have a worse overall prognosis and earlier disease relapse." (PMID 22952779, 2012). "In addition, colon cancer patients with high NAG-1/GDF15 levels exhibit longer survival, according to our analysis of TCGA data." (PMID 40316530, 2025). "Therefore, we categorized the tested lung and colon cancer cell lines in two groups depending on GDF15 reduction and GDF11 induction upon BET inhibition and explored differences in protein expression, gene dependency, drug sensitivity and metabolites." (PMID 37495707, 2023). "Future studies should focus on the mechanism through which GDF15 is repressed in these cells; this finding could provide new strategies for the diagnosis and gene therapy of colon cancer." (PMID 33062674, 2020). "Our research provided evidence that GDF15 may act as a tumor suppressor in cancer cells, and low expression of the protein contributes to the development of 5-FU resistance in colon cancer." (PMID 33193874, 2020). "It has been previously reported that GDF15 could promote colon cancer invasion and metastasis by activating c-Fos." (PMID 33123476, 2020). "More recently, GDF15 has been identified as a highly robust senescence-associated secretory phenotype (SASP) factor in multiple senescence inducers and cell types as well as a driver of senescence-associated colon cancer metastasis." (PMID 33210602, 2020). "Our previous results showed that growth differentiation factor 15 (GDF15) is downregulated in HCT-15/FU drug-resistant colon cancer cells compared with drug-sensitive colon cells; these cells also showed accelerated proliferation and angiogenesis in vitro and in vivo." (PMID 33062674, 2020). "A pharmacological agent that coordinately upregulated GDF15 and EGR1 in a colon cancer cell line also activated transcription at a region in the GDF15 promoter containing 2 experimentally validated EGR1 binding sites, suggesting that EGR1 is a direct transcriptional regulator of GDF15." (PMID 32310257, 2020). "GDF-15 in plasma has previously been proposed as a biomarker in endometrial cancer, and has also been suggested as a serum biomarker in patients with prostate, pancreatic and colon cancers." (PMID 30645608, 2019). "Combining the expression trends of these genes in colon cancer and after aspirin treatment, we found that aspirin further upregulated NOX4, CXCL8, CXCL5, LIF, GDF15, and MMP13, while stimulated inhibition of IL2, NCF1, and PTGS1." (PMID 41425852, 2025). "In this study, we showed that upregulation of NAG-1/GDF15 decreases, while downregulation of NAG-1/GDF15 increases β-catenin and NF-κB activity in colon cancer cell lines." (PMID 40316530, 2025).
colon carcinoma (continued). "GDF-15 is also called as nonsteroidal anti-inflammatory drug (NSAID) activated gene-1 (NAG-1), because it was identified as an NSAID-induced gene based on the evidence that the development of colon cancer was prevented by the administration of NSAIDs16,17." (PMID 36008442, 2022). "Another factor in exosomes that promotes muscle wasting is growth differentiation factor 15 (GDF-15), identified in the exosomes of CT26 colon cancer cells." (PMID 36072935, 2022). "Interestingly, the transcript level of GDF15 in HCT116 cells (10.20) was higher than in SW480 cells (9.24), highlighting the potential impact of GDF15 in the proliferation of colon cancer cells." (PMID 39108882, 2024). "To enable experiments with an anti-human GDF-15 antibody, we selected the MC38 colon cancer cell line, which showed no detectable expression of murine GDF-15 under standard conditions." (PMID 37474523, 2023). "Intraperitoneal perfusion therapy targeting the GDF15-POSTN axis may reduce intraperitoneal metastasis and the formation of ascites in patients with colon cancer, but this approach needs to be further validated in vivo and in clinical trials." (PMID 33193874, 2020). "Last but not least, GDF-15 levels have been found elevated in the serum of patients with metastatic BC, prostate, and colon cancer while its role with regard to cell invasion is controversial indicating a possible cell-type-specific mechanism of action." (PMID 30621163, 2019). "However, the role of GDF15, especially in 5-FU resistance in colon cancer, is not yet fully understood." (PMID 33062674, 2020). "Colon cancer patients with upregulated NOX4, CXCL8, CXCL5, GDF15, or MMP13 may not benefit from aspirin chemoprophylaxis." (PMID 41425852, 2025). "Although it has been reported that GDF15 can activate the downstream pathway through TGF-βR in some specific cells (e.g., cardiomyocytes, colon cancer cells, etc.), it is not clear whether GDF15 can act through TGF-β family receptors because of the purification of recombinant proteins." (PMID 37723495, 2023).
atrial fibrillation (53 papers, 2015 to 2026). A disorder characterized by an electrocardiographic finding of a supraventricular arrhythmia characterized by the replacement of consistent P waves by rapid oscillations or fibrillatory waves that vary in size, shape and timing and are accompanied by an irregular ventricular response. "In the context of cardiac surgery, elevated levels of GDF15 have been linked to postoperative atrial fibrillation and unfavorable outcomes, primarily due to myocardial and renal injury." (PMID 39766300, 2024). "In patients with atrial fibrillation (AF), GDF-15 has been identified as a risk factor for bleeding events." (PMID 36836162, 2023). "Higher GDF-15 levels have been associated with bleeding risk particularly in patients with atrial fibrillation and after acute coronary syndromes." (PMID 35455481, 2022). "GDF-15 has been found to be an independent risk factor for a composite endpoint of major bleeding events in patients with atrial fibrillation on oral anticoagulants and in patients with acute coronary syndrome on dual antiplatelet therapy." (PMID 34177769, 2021). "Sharma A reported in the ARISTOTLE trial which included 18 201 patients with atrial fibrillation that GDF-15 was the strongest marker associated with bleeding death." (PMID 32746821, 2020). "Higher levels of NT-proBNP, hs-TnT, RDW and GDF-15 were associated with the presence of atrial fibrillation." (PMID 32715081, 2020). "In addition, there is evidence proposed that the GDF15 serum level appears to be linked with stroke in patients with atrial fibrillation." (PMID 36140453, 2022). "However, a previous study GDF15 levels were positively associated with ACE2 levels in patients with atrial fibrillation." (PMID 35937703, 2022). "In addition, there is evidence proposed that GDF15 serum level appears to be linked with stroke in patients with atrial fibrillation." (PMID 36444166, 2022). "Although there are no studies associating TIMP4 with GDF-15; this extracellular matrix protein has been associated with atrial fibrillation, which could help understand the relationship between GDF-15 and this arrhythmia." (PMID 34441356, 2021). "Also, other factors such as atrial fibrillation, valvular disease, etc., that cause cardiac stress might have an impact on GDF-15 levels." (PMID 39768671, 2024). "GDF-15 is a stress-responsive member of the transforming growth factor-β superfamily associated with fibrotic processes and inflammation, which could explain its relationship with cardiovascular disease and outcomes; namely, atrial fibrillation." (PMID 34441356, 2021). "Circulating concentrations of soluble ST2, growth differentiation factor-15 (GDF-15), and high-sensitivity troponin I (hsTnI) are associated with incident atrial fibrillation (AF)." (PMID 25949827, 2015). "Concentrations of GDF-15 increase in various CV conditions, including acute and chronic HF, atrial fibrillation and acute coronary syndromes." (PMID 39200768, 2024). "The higher prevalence of history of MI, angina pectoris and atrial fibrillation in particular, goes along the same line of evidence on GDF-15, a cytokine produced in cardiovascular cells under the effect of inflammation and oxidative stress." (PMID 34217226, 2021). "GDF‐15 has also been found to predict bleeding complications in atrial fibrillation or acute coronary syndrome, which may be explained by the inhibitory effects of GDF‐15 on platelet activation." (PMID 41555670, 2026). "A substantial body of evidence supports the prognostic utility of GDF-15 in patients with acute coronary syndrome and HF, as well as its usefulness for predicting bleeding complications in acute pulmonary embolism and atrial fibrillation in patients on anticoagulation therapy." (PMID 39407996, 2024). "Consequently, GDF-15 has been proposed as a novel biomarker for bleeding events and has been included in the novel ABC-bleeding risk score for patients with atrial fibrillation." (PMID 35455481, 2022).